CDC50A (cell division cycle 50 P4-ATPase accessory subunit A)
Description:
Accessory component of a P4-ATPase flippase complex which catalyzes the hydrolysis of ATP coupled to the transport of aminophospholipids from the outer to the inner leaflet of various membranes and ensures the maintenance of asymmetric distribution of phospholipids. Phospholipid translocation also seems to be implicated in vesicle formation and in uptake of lipid signaling molecules. The beta subunit may assist in binding of the phospholipid substrate. Required for the proper folding, assembly and ER to Golgi exit of the ATP8A2:TMEM30A flippase complex. ATP8A2:TMEM30A may be involved in regulation of neurite outgrowth, and, reconstituted to liposomes, predomiminantly transports phosphatidylserine (PS) and to a lesser extent phosphatidylethanolamine (PE). The ATP8A1:TMEM30A flippase complex seems to play a role in regulation of cell migration probably involving flippase-mediated translocation of phosphatidylethanolamine (PE) at the plasma membrane. Required for the formation of the ATP8A2, ATP8B1 and ATP8B2 P-type ATPAse intermediate phosphoenzymes. Involved in uptake of platelet-activating factor (PAF), synthetic drug alkylphospholipid edelfosine, and, probably in association with ATP8B1, of perifosine. Also mediates the export of alpha subunits ATP8A1, ATP8B1, ATP8B2, ATP8B4, ATP10A, ATP10B, ATP10D, ATP11A, ATP11B and ATP11C from the ER to other membrane localizations.
Synonyms: TMEM30A; C6orf67; FLJ10856
Tractability: Small molecule: a structure with a bound ligand is known. Antibody: its Gene Ontology location is reachable by antibodies, with high confidence; UniProt places it where antibodies can reach, with medium confidence; UniProt predicts a signal peptide or a membrane-spanning region. PROTAC: ubiquitination databases record sites on it; its protein half-life has been measured.
Gene: Protein-coding gene on chromosome 6 (75,252,924 to 75,284,948, reverse strand). Ensembl gene ENSG00000112697.
Subcellular location: Membrane; Cell membrane; Golgi apparatus; Cytoplasmic vesicle, secretory vesicle membrane; Apical cell membrane
Pathways (Reactome):
Immune System: Neutrophil degranulation
Gene Ontology:
Molecular function: aminophospholipid flippase activity; protein binding; structural molecule activity
Biological process: aminophospholipid transport; endosomal transport; phospholipid translocation; positive regulation of phospholipid translocation; protein localization to endosome; xenobiotic transmembrane transport; aminophospholipid translocation; positive regulation of neuron projection development
Cellular component: early endosome membrane; endoplasmic reticulum; late endosome membrane; membrane; phospholipid-translocating ATPase complex; plasma membrane; azurophil granule membrane; specific granule membrane; apical plasma membrane; Golgi apparatus; transport vesicle membrane
Genetic constraint (gnomAD): Loss-of-function variants: 14 observed, 24.16 expected, observed/expected ratio (o/e) 0.58, 90% interval 0.38 to 0.91. The upper end of that interval is the gene's LOEUF score, 0.91, which puts it in group 3 of 6, group 1 being the genes least tolerant of losing a copy. Missense variants: 260 observed, 345.21 expected, observed/expected ratio (o/e) 0.75, 90% interval 0.68 to 0.83. Synonymous variants: 107 observed, 127 expected, observed/expected ratio (o/e) 0.84, 90% interval 0.72 to 0.99.
Homologues: Orthologues: chimpanzee TMEM30A (100% identical), macaque TMEM30A (99% identical), rabbit TMEM30A (95% identical), dog TMEM30A (94% identical), pig TMEM30A (91% identical), rat Tmem30a (90% identical), mouse Tmem30a (89% identical), tropical clawed frog tmem30a (76% identical), zebrafish tmem30ab (73% identical), zebrafish tmem30aa (72% identical), Drosophila melanogaster Cdc50 (52% identical), Caenorhabditis elegans chat-1 (45% identical), and 2 more. Paralogues in human: CDC50B (50% identical).
Diseases named in the same sentence as CDC50A in open-access papers:
CDC50A is named in the same sentence as 41 diseases in open-access papers, as found by Europe PMC text mining. Sharing a sentence is not in itself a finding about the gene and the disease. The quoted sentences say what the papers report.
intrahepatic cholestasis (4 papers, 2018 to 2025). A cholestasis characterized by impairment of the bile flow caused by obstruction located in the liver. "The recent study reporting that mice deficient in liver CDC50A (TMEM30A) exhibit severe intrahepatic cholestasis supports the importance of ATP8B1-CDC50A and ATP11C-CDC50A complexes in bile salt homeostasis." (PMID 30018401, 2018).
diffuse large B-cell lymphoma (3 papers, 2022 to 2025). "CDC50A loss-of-function mutations were associated with favourable outcomes uniquely observed in diffuse large B-cell lymphoma." (PMID 35982417, 2022).
leukemia (3 papers, 2023 to 2025). A malignant (clonal) hematologic disorder, involving hematopoietic stem cells and characterized by the presence of primitive or atypical myeloid or lymphoid cells in the bone marrow and the blood. "Our research has identified c-KitmidCD3+Lin- leukemia stem cells in Pten-null T acute leukemia mice, CD166+CD49fhiCD104-Lin- CSC in human NSCLC tumors, and CDC50A+Lin- CSC in human ovarian tumors." (PMID 41453945, 2025).
colorectal cancer (2 papers, 2017 to 2022). A primary or metastatic malignant neoplasm that affects the colon or rectum. "In addition, overexpression of CDC50A also conferred resistance to oxaliplatin in colorectal cancer patients." (PMID 35982417, 2022).
ovarian carcinoma (1 paper, 2022). A malignant neoplasm originating from the surface ovarian epithelium. "Twenty-three primary cancer tissues were collected from ovarian cancer patients, and CDC50A+Lin− cells were sorted by FACS." (PMID 35982417, 2022). "These biological behaviours of CDC50A+ ovarian cancer cells were consistent with those of ovarian cancer cells with positive expression of several classic stem cell surface biomarkers, such as CD44, CD117, CD24 and CD133." (PMID 35982417, 2022). "Second, if all is known about the tumour heterogeneity of ovarian cancer, why does the ratio of CDC50A-positive cells vary so significantly among different tissues?" (PMID 35982417, 2022). "The ratios of CDC50A+ Lin− in the 22 primary ovarian cancer tumours before neoadjuvant chemotherapy ranged from 0.6 to 12.8% (average 9.62%)." (PMID 35982417, 2022). "Higher expression of CDC50A was detected in SP ovarian cancer cells, which were rich in cancer initiation ability." (PMID 35982417, 2022). "CDC50A-positive cells (0.4% ~ 2.0%) were shown in ovarian cancer cells, which was similar to other common biomarkers of cancer stem cells." (PMID 35982417, 2022). "CDC50A-positive cells from cell lines and primary ovarian cancer tissues were validated to show characteristics of cancer-initiating cells both in vitro and in vivo, including sphere-forming, self-renewal, differentiation, tumor metastasis and tumorigenicity in mice." (PMID 35982417, 2022). "In contrast, only a few of the CDC50A−Lin− cells (2.3%) were vimentin positive, suggesting that CDC50A+ cells are more mesenchymal-like and may participate in the dissemination and metastasis of ovarian cancers." (PMID 35982417, 2022). "For the first time, it was validated that CDC50A might be correlated with ovarian cancer development." (PMID 35982417, 2022). "CDC50A could be used to screen ovarian cancer-initiating cells and might be a new target to resolve tumour development in EOC patients." (PMID 35982417, 2022). "CDC50A could be used as a biomarker of ovarian cancer-initiating cells and might be a novel target to promote prognosis." (PMID 35982417, 2022). "Furthermore, the ratios of CDC50A-positive cells in five other ovarian cancer cell lines, in addition to SKOV3 and A2780 cells, were evaluated by flow cytometry." (PMID 35982417, 2022). "In this work, CDC50A was located at the cell membrane of ovarian cancer cells." (PMID 35982417, 2022). "Because of the more reasonable proportion of positive cells in 5 EOC cell lines than in other common CSC biomarkers, such as CD44, CD117 and CD133, CDC50A might be a candidate biomarker of epithelial ovarian cancer-initiating cells." (PMID 35982417, 2022). "Finally, the mechanism by which CDC50A regulates ovarian cancer cell proliferation and metastasis is still unknown." (PMID 35982417, 2022). "Notably, CDC50A, not CD59, was selected as a potential surface biomarker for epithelial ovarian cancer-initiating cells because of the more reasonable proportion (nearly 1%) of positive cells." (PMID 35982417, 2022).
ovarian serous carcinoma (1 paper, 2022). "Among 16 high-grade ovarian serous cancer patients, a high ratio of CDC50A-positive cells in primary tumours was correlated with a shorter platinum-free interval (p = 0.031, HR 0.260, 95% CI 0.77 ~ 0.885)." (PMID 35982417, 2022).
ovarian tumours (1 paper, 2022). "The frequency of CDC50A+Lin− cells was associated with the dissemination and metastasis of ovarian tumours." (PMID 35982417, 2022). "Taken together, these data demonstrated that CDC50A+Lin− cells from primary ovarian tumours have the ability to self-renew and differentiate in vivo." (PMID 35982417, 2022). "The tumorigenicity of CDC50A+Lin− cells sorted from ovarian tumours was then assessed using Nod;Scid;IL2rγ−/− (NSG) immunocompromised mice." (PMID 35982417, 2022). "The frequencies of CDC50A+Lin− cells were significantly higher in the metastatic tumours than in the corresponding primary ovarian tumours." (PMID 35982417, 2022). "Isolated CDC50A+Lin− cells from primary ovarian tumours were cultured in vitro." (PMID 35982417, 2022). "Furthermore, these CDC50A+Lin− cells from primary ovarian tumours could be sorted and passaged in NSG recipient mice." (PMID 35982417, 2022).
tumor (12 papers, 2017 to 2025). "The relationship between CDC50A-positive cells from primary tissues and tumour metastasis was confirmed based on their mesenchymal transition characteristics." (PMID 35982417, 2022). "Both in vitro and in vivo, it was confirmed that CDC50A+ cells meet the criteria of cancer stem cells, such as proliferation, self-renewal, differentiation, tumorigenicity and tumour metastasis." (PMID 35982417, 2022). "CDC50A loss-of-function increases the accumulation of chemotherapy drugs and tumour-associated macrophages and the effect of anti-CD47 blockade, limiting tumour growth." (PMID 35982417, 2022). "Although the detailed mechanisms by which tumor cells dysregulate calcium and in turn contribute to PS externalization are still emerging, interesting proof-of-concept studies by Wang and colleagues established “a PS out” tumor model by targeting the PS flippase component CDC50A." (PMID 40069722, 2025). "0.6% ~ 49.5% of CDC50A+ cells were found in the Lin− tumour cell population." (PMID 35982417, 2022). "Third, can CDC50A-positive cells be the reason for tumour recurrence?" (PMID 35982417, 2022). "Thus, CDC50A+Lin− cells are increased both in tumours after neoadjuvant chemotherapy and in metastasized tumours." (PMID 35982417, 2022). "Notably, a high ratio of CDC50A-positive cells in primary tumour tissues was correlated with poor prognosis in the clinic." (PMID 35982417, 2022). "Notably, only small percentages of the xenograft tumour cells were CDC50A+, apparently capitulating to the development of original human tumours." (PMID 35982417, 2022). "Inoculations of 103, 104 or 105 CDC50A+Lin− cells were able to develop xenograft tumours in one-fourth, three-eighth or four-fifth of mice, respectively, whereas only administration of 105 CDC50A−Lin− cells was able to generate tumours in a quarter of mice." (PMID 35982417, 2022). "Indeed, knockout of CDC50A, a subunit of ATP11C that participates in PS flipping, increases tumor-associated macrophages and enhances the effect of anti-CD47 blockade on limiting tumor growth." (PMID 32802188, 2020). "Indeed, very interesting studies by Wang and colleagues recently established constitutively “PSout” live tumor cells by knocking out the TMEM30 (CDC50A) subunit of P4 ATPases, a family of flippases that vectorially transfer PS from the outer surface to the inner surface of the plasma membrane." (PMID 41198619, 2025). "Another study demonstrated the development of PSout tumor models with tumor cells lacking PS, the flippase component CDC50A, constantly exposing PS but alive." (PMID 37686603, 2023). "Inoculation of as few as 102 CDC50A+ cells resulted in the formation of tumours in 50% of the mice, whereas no tumours were found after 103 CDC50A− cells were administered." (PMID 35982417, 2022).
cancer (4 papers, 2017 to 2025). A tumor composed of atypical neoplastic, often pleomorphic cells that invade other tissues. "Both in cell lines and primary EOC, cancer-initiating biofunctions of CDC50A positive cells were validated." (PMID 35982417, 2022). "The percentage of CDC50A-positive cells in primary cancer tissues ranged from 0.6 to 7.4%." (PMID 35982417, 2022). "Interestingly, CDC50A has also been reported to play a role in the uptake of the anticancer drug perifosine in human carcinoma." (PMID 35982417, 2022).
CDC50A also shares sentences with these, for which no sentence is quoted: anemia (2 papers); Ataxia (2); cerebellar ataxia (2); Cerebellar atrophy (2); focal segmental glomerulosclerosis (2); Glomerular sclerosis (2); prostate carcinoma (2); acute leukemia (1); Allergy (1); Alzheimer disease (1); cervical adenocarcinoma (1); chronic myelocytic leukemia (1); dementia (1); endometrial carcinoma (1); glaucoma (1); glomerular disease (1); hearing loss (1); hepatocellular carcinoma (1); infection (1); ischemia (1); ischemic stroke (1); lymphoma (1); mantle cell lymphoma (1); membranous nephropathy (1); metabolic disorders (1); nephrotic syndrome (1); neuroblastoma (1); pancreatic cancer (1); renal disease (1); squamous cell carcinoma (1).
A further 2 diseases each share a sentence with CDC50A in 1 paper.